SMAD3 (SMAD family member 3)
Diseases named in the same sentence as SMAD3 in open-access papers (continued):
Sharing a sentence is not in itself a finding about the gene and the disease.
lung adenocarcinoma (41 papers, 2016 to 2025). A carcinoma that arises from the lung and is characterized by the presence of malignant glandular epithelial cells. "To delineate the transcriptional networks associated with SMAD3 in stage-dependent lung adenocarcinoma progression, we performed an integrative bioinformatic analysis combining differential expression and correlation analyses." (PMID 40361382, 2025). "This gene set represents a stage-relevant SMAD3-associated transcriptional program potentially driving lung adenocarcinoma progression." (PMID 40361382, 2025). "TAFs play an important role in tumour microenvironment (TME)-driven cancer progression, and in lung adenocarcinoma-associated fibroblasts, SMAD3 expression is elevated, promoting fibroblast migration." (PMID 37685308, 2023). "Similar to previous studies, we also found that the expression level of SMAD3 was significantly associated with the prognoses of thousands of patients with lung adenocarcinoma." (PMID 32140069, 2020). "The results of the cell proliferation assay demonstrated that overexpression of p21 reversed the inhibition of proliferation caused by SMAD3 knockdown in all three lung adenocarcinoma cell lines." (PMID 32140069, 2020). "Overexpression of miR-136 results in the inhibition of metastasis-associated traits in lung adenocarcinoma cells via Smad2 and Smad3." (PMID 31195953, 2019). "In lung adenocarcinoma, tumor-associated macrophages promote ezrin-phosphorylation-mediated epithelial-mesenchymal transition through fucosyltransferase IV-induced fucosylation, in which upregulation of phospho-Smad3 plays a pivotal role." (PMID 33046439, 2021). "The correlation landscape between SMAD3 and differentially expressed genes in lung adenocarcinoma (LUAD) demonstrates significant functional pathway convergence." (PMID 40361382, 2025). "Metformin, an AMPK activator, inhibits the TGF-β-induced increase in Smad2 and Smad3 phosphorylation in A549 lung adenocarcinoma cells." (PMID 41392217, 2025). "The intersection of differentially expressed genes between advanced (stages III–IV) and early (stages I–II) lung adenocarcinoma with genes significantly correlated with SMAD3 expression yielded 1626 high-confidence candidates." (PMID 40361382, 2025). "To evaluate the clinical relevance of SMAD3 in lung adenocarcinoma (LUAD) progression, we performed comprehensive immunohistochemical and comparative expression analyses across tumor stages." (PMID 40361382, 2025). "Analysis using the UALCAN and DNMIVD databases showed significantly lower DNA methylation levels of the SMAD3 promoter region in lung adenocarcinoma (LUAD) and lung squamous cell carcinoma (LUSC) tissues compared to normal tissues." (PMID 38493128, 2024). "Aligning with these findings, SMAD3 expression significantly differs between radiation-resistant and radiation-sensitive patients; SMAD3 knockdown markedly inhibits cell growth and boosts radiosensitivity of lung adenocarcinoma cells both in vitro and in vivo." (PMID 38493128, 2024). "In the present study, we elucidated the pathway that induces RhoA activation downstream of Smad3, using A549 lung adenocarcinoma cells." (PMID 38141763, 2024). "This suggests that SMAD3 is a potential prognostic and radiosensitivity indicator and a target for radiotherapy and other treatments for lung adenocarcinoma patients." (PMID 37685308, 2023). "SMAD3 knockdown significantly inhibits lung adenocarcinoma cell growth and increases radiosensitivity via P21." (PMID 37685308, 2023). "SMAD3-responsive HCP5 contributes to lung adenocarcinoma metastasis by targeting miR-203/SNAI signaling." (PMID 35602292, 2022). "Analyses based on clinical specimens showed that AHNAK2 regulated the EMT via a TGF-β/Smad3 pathway in lung adenocarcinoma and a hypoxia inducible factor-1α/zinc finger E-box-binding homeobox 1 (HIF-1/ZEB1) pathway in clear cell renal cell carcinoma." (PMID 33918555, 2021).
lung adenocarcinoma (continued). "We found that knockdown of SMAD3 using two short hairpin RNAs in lentivirus vectors significantly inhibited cell growth and increased radiosensitivity of the lung adenocarcinoma cell lines A549, H1299, and H1975." (PMID 32140069, 2020). "Here, we report that the transcription factor SMAD3 inhibited cell growth and promote radiosensitivity of lung adenocarcinoma both in vitro and in vivo via p21/cell cycle." (PMID 32140069, 2020). "The purpose of this study was to investigate the effect and mechanism of SMAD3 on the radiosensitivity of lung adenocarcinoma in vitro and in vivo." (PMID 32140069, 2020). "Overall, the data in this study indicated that SMAD3 was a potential indicator of prognosis and radiosensitivity as well as a target for radiotherapy and other treatments of lung adenocarcinoma." (PMID 32140069, 2020). "To explore the role of SMAD3 in lung adenocarcinoma, we detected changes in gene expression following SMAD3 knockdown in A549 cells using RNA-Seq." (PMID 32140069, 2020). "Tissue microarrays was used to investigate the expression of SMAD3 and p21 in the tumor samples of 119 lung adenocarcinoma patients who underwent surgery in our department." (PMID 32140069, 2020). "In summary, we determined that SMAD3 regulated radiosensitivity in lung adenocarcinoma via p21 in vitro and in vivo." (PMID 32140069, 2020). "We also used GEPIA to analyze the correlation between the expression of SMAD3 and p21 in TCGA lung adenocarcinoma patients, and found that the level of SMAD3 and p21 are highly positively correlated (R = 0.28, p < 0.001)." (PMID 32140069, 2020). "To explore the role of SMAD3 in non-small cell lung cancer, we designed two different shRNAs targeting SMAD3, and transfected them into three lung adenocarcinoma cell lines to knockdown SMAD3 expression." (PMID 32140069, 2020). "Our results indicate that SMAD3 is a potential prognosis and radiosensitivity indicator as well as a target for radiotherapy and other treatments of patients with lung adenocarcinoma." (PMID 32140069, 2020). "In the present study, we found that knockdown of SMAD3 resulted in significant inhibition of cell growth via p21/cell cycle in lung adenocarcinoma cells and a mouse model." (PMID 32140069, 2020). "In this study, we found that knockdown of SMAD3 by two shRNAs inhibited cell growth and promoted the radiosensitivity of three lung adenocarcinoma cell lines." (PMID 32140069, 2020). "In short, p21 overexpression reversed the effect of SMAD3 on cell growth and the radiosensitivity of lung adenocarcinoma cells in vivo, which was consistent with the in vitro results." (PMID 32140069, 2020). "Because TGF-β1 can induce p-Smad3 expression, we treated lung adenocarcinoma cells with different concentrations of TGF-β1 (0–20 ng/ml)." (PMID 28005074, 2016). "PREP1, together with the AP-1 member, FRA1, transactivate an enhancer of the Smad3 gene, providing a more sensitive response of lung adenocarcinoma cells to TGFβ." (PMID 27367735, 2016). "We investigated the roles of Smad3-regulated miRNAs with respect to lung adenocarcinoma cell apoptosis, proliferation, and metastasis." (PMID 28005074, 2016). "The CCAAT/enhancer-binding proteins α and β (C/EBPα and β) are reported to be downstream factors of TRIB2.24, 25 To investigate the effects of Smad3-related miRNAs on C/EBPα and β expression, lung adenocarcinoma cells were treated with miR-140 and miR-206." (PMID 28005074, 2016). "We found that miR-206 was down-expressed in lung adenocarcinoma samples and that miR-206 and miR-140 can inhibit lung adenocarcinoma cell proliferation in vitro and in vivo by downregulating new target-Smad3." (PMID 28005074, 2016). "MiR-206 and miR-140 inhibited lung adenocarcinoma cell proliferation in vitro and in vivo by suppressing p-Smad3/Smad3 and TRIB2." (PMID 28005074, 2016).
lung adenocarcinoma (continued). "Unexpectedly, SMAD3 phosphorylation was negatively correlated with the percentage of N1 cells in total CD16b+ TANs but did not correlate with the percentage of N2 TANs in patients with lung adenocarcinoma in our patient cohort (n = 72)." (PMID 37002229, 2023). "Nevertheless, one previous study has shown that LINC00842 was induced by TGF-β stimulation via the TGF-β/SMAD pathway in TGF-β-responsive cell lines, such as human hepatocarcinoma Huh7 and lung adenocarcinoma A549 cells, and then targeted SMAD3 to promote epithelial–mesenchymal transition." (PMID 34158490, 2021). "Similarly, miR-206 and miR-140 suppress lung adenocarcinoma cell proliferation and metastasis via reduced phospho-Smad3/Smad3, which downregulate TRIB2." (PMID 34070799, 2021). "Moreover, the level of SMAD3 and p21 expression was negatively correlated with OS of lung adenocarcinoma patients." (PMID 32140069, 2020). "Moreover, the number of lung adenocarcinoma cell colonies was significantly decreased compared with SMAD3-NC by single target multi-shot model curve fitting." (PMID 32140069, 2020). "We then showed that knockdown of SMAD3 significantly reduced expression of cyclin-dependent kinase inhibitor 1 (p21) and increased the proportion of G2/M phase cells and the radiosensitivity of lung adenocarcinoma." (PMID 32140069, 2020). "In order to understand the upstream mechanism of downregulation of Smad3 by smoking, we performed miRNA microarray analyses after treating human lung adenocarcinoma A549 and immortalized peripheral lung epithelial HPL1A cells with cigarette smoke condensate (CSC)." (PMID 32668597, 2020). "As tumor suppressors, miR-206 and miR-140 can inhibit lung adenocarcinoma cell metastasis by increasing E-cadherin and decreasing α-SMA expression, and suppress lung adenocarcinoma cell growth in vivo by decreasing oncogenic TRIB2 promoter activity through Smad3." (PMID 28005074, 2016). "Interestingly, we detected a strong positive correlation between Runx1 and Smad3 in the lung adenocarcinoma TCGA cohort at transcriptome level (p = 5.4 × 10−14), which was further confirmed in our NSCLC cohort with multiplex IHC staining at protein level (p = 0.0008)." (PMID 37967345, 2024). "SMAD3 may be a potential indicator of the radiosensitivity of patients with lung adenocarcinoma." (PMID 32140069, 2020). "Moreover, genome-wide chromatin occupancy analysis using lung adenocarcinoma cells has revealed that NKX2-1 colocalizes with Smad3 to regulate a subset of genes while competing with Smad3-Smad4 complex formation resulting in altered genomic binding profiles of Smad3." (PMID 30127261, 2018). "We observed there might be a negative feedback loop between miR-206 (or miR-140) and TGF-β1 whereby these two miRNAs, downregulated by TGF-β1, participated in Smad3-dependent TGF-β1 signaling and negatively regulated TGF-β1/Smad3 signals in lung adenocarcinoma." (PMID 28005074, 2016). "To investigate the immunomodulatory roles of SMAD3 in lung adenocarcinoma (LUAD), we performed comprehensive correlation analyses between SMAD3 expression and immune parameters across multiple algorithmic platforms." (PMID 40361382, 2025). "These multidimensional analyses collectively suggest a previously unappreciated functional relationship between SMAD3 and NOTCH signaling in lung adenocarcinoma pathogenesis." (PMID 40361382, 2025). "In A549 lung adenocarcinoma cells, activation of the Erk and p38 MAPK pathways occurs independently from Smad3 at 1 h after stimulation, whereas it is dependent on Smad3 at 4 h (Erk) or 16 h (p38 MAPK) after stimulation." (PMID 38569937, 2024). "In conclusion, we provide insight into the biological function of AK2 in human lung adenocarcinoma and demonstrate that AK2 overexpression activates the TGF-β/Smad3/Smad2/Smad4 signaling pathway, leading to enhanced invasion via EMT." (PMID 34630090, 2021).
lung adenocarcinoma (continued). "Currently, an increasing number of reports show that Smad3 can promote invasion and metastasis by EMT in various cancers, such as lung adenocarcinoma, prostate cancer and pancreatic ductal adenocarcinoma." (PMID 29880900, 2018). "Smad3 interacts and cooperates with HDAC6 during EMT in A549 lung adenocarcinoma cells; HDAC6 is well known as a regulator of tubulin acetylation causing microtubule instability and blocking cell migration." (PMID 27367735, 2016). "In summary, miR-206 and miR-140, as tumor suppressors, induced lung adenocarcinoma cell death and inhibited cell proliferation by modifying oncogenic TRIB2 promoter activity through p-Smad3." (PMID 28005074, 2016). "Specifically, miR-206 and miR-140 suppressed lung adenocarcinoma proliferation in vitro and in vivo by decreasing TRIB2 through Smad3 in TGF-β1 pathway." (PMID 28005074, 2016). "Through knockdown experiments in A549 lung adenocarcinoma cells, we found that Smad3-mediated induction of Snail, but not that of Slug, is indispensable for morphological changes, stress fiber formation, and enhanced motility in cells stimulated with TGF-β." (PMID 38141763, 2024). "Additionally, we previously demonstrated that TRIB2 has an oncogenic role in lung adenocarcinoma, and miR-206 can modify TRIB2 promoter activity through p-Smad3." (PMID 35790734, 2022). "Therefore, TGF-β regulates the transcription of LINC00152 through SMAD3, and maintains the stability of LINC00152 mRNA through HuR, hence achieving high expression of LINC00152 in lung adenocarcinoma tissues." (PMID 36071042, 2022). "A novel lncRNA ELIT-1, Smad3, and Snail form a positive feedback loop by recruiting Smad3 (Sekelsky mothers against dpp 3) to the promoter of Snail, other TGF-β-target genes, and ELIT-1 itself, enhancing TGF-β/Smad3 signaling and promoting EMT progression in lung adenocarcinoma (LUAD) and GC." (PMID 31575017, 2019). "We measured Smad3 and TRIB2 expression in lung adenocarcinoma samples." (PMID 28005074, 2016). "Inclusion of Smad3 phosphorylation inhibitors in lung adenocarcinoma cells did not affect the regulation of cell migration, invasion and EMT by TGF-β1 with or without knockdown of AHNAK2, suggesting that AHNAK2 promotes lung adenocarcinoma progression through the TGF-β1/Smad3 pathway." (PMID 38033502, 2023).
aneurysm (38 papers, 2013 to 2025). Bulging or ballooning in an area of an artery secondary to arterial wall weakening. "Another example is aneurysm-osteoarthritis syndrome, an inherited autosomal dominant connective tissue disease caused by SMAD3 mutations." (PMID 39992457, 2025). "Smad3 is a downstream transcription factor in the TGFβ signalling pathway; mutations in SMAD3 can cause an aneurysms-osteoarthritis syndrome with features of craniofacial and skeletal abnormalities." (PMID 36653343, 2023). "Our finding expands the spectrum of variants that are associated with TAA/D and further strengthens the connection between the presence of aneurysm phenotype and SMAD3 variants." (PMID 32597575, 2020). "Background and objectives: Loeys–Dietz syndrome 3, also known as aneurysms-–osteoarthritis syndrome, is an autosomal dominant genetic connective tissue disease caused by pathogenic variants in SMAD3, a transcription factor involved in TGF-β signaling." (PMID 31096651, 2019). "Using CT or MRI, 3D reconstruction of images from the head to pelvis is needed to identify arterial tortuosity, present in most individuals with a TGFBR1/2, TGFB2, or SMAD3 mutation, and aneurysms in the rest of the arterial tree." (PMID 29392890, 2018). "All three cases harbor a pathogenic variant in the SMAD3 gene, known to cause aneurysm osteoarthritis syndrome, Loeys‐Dietz syndrome type 3 or isolated Heritable Thoracic Aortic Disease." (PMID 29717556, 2018). "Missense mutations in a conserved protein domain of SMAD3 have been linked to aneurysm-osteoarthritis syndrome, a congenital disorder characterised by arterial aneurysms, heart abnormalities and early-onset OA." (PMID 28934396, 2017). "Analysis of SMAD3 in 99 patients with thoracic aortic aneurysms and dissections and Marfan-like features revealed a heterozygous SMAD3 mutation, as well as another 5 novel SMAD3 mutations in 5 additional families with aneurysms-osteoarthritis syndrome." (PMID 27218255, 2016). "Aneurysms-osteoarthritis syndrome (AOS) is an autosomal dominant disorder caused by mutation in the SMAD3 gene encoding protein that is essential for TGF-β signal transduction." (PMID 26221609, 2015). "Aneurysms-osteoarthritis syndrome (AOS) caused by haploinsufficiency of SMAD3 is a recently described cause of syndromic familial thoracic aortic aneurysm and dissection (TAAD)." (PMID 24711937, 2014). "Ninety percent of the patients carrying distinct SMAD3 mutations develop aortic aneurysms and dissections, called aneurysms‐osteoarthritis syndrome (AOS)." (PMID 23782924, 2013). "Therefore, the syndrome caused by SMAD3 mutations is called “aneurysms–osteoarthritis syndrome” (AOS)." (PMID 35517795, 2022). "SMAD3 mutations play an important role in familial aortic diseases, characterized by aneurysms." (PMID 35234888, 2022). "Although his skeletal symptoms were not evident, this patient underwent a targeted NGS because of a suspected familial SD and was diagnosed with Loeys-Dietz syndrome type 3 (aneurysms-osteoarthritis syndrome) caused by a pathologic variant in SMAD3, which was inherited from his mother." (PMID 34122524, 2021). "Thereby, Ilk conditional mutant mice might prove useful as a model to study aortic aneurysms caused by reduced Smad3 signaling, which is known to be a feature of aneurysms-osteoarthritis syndrome." (PMID 23744273, 2013). "These vascular anomalies, which are a feature of Marfan, Ehlers-Danlos and Loeys-Dietz syndromes as well as the newly described aneurysms-osteoarthritis syndrome, can be caused by mutations affecting the extracellular matrix, smooth muscle contractile proteins or Smad3 signaling factors." (PMID 23744273, 2013).